Y_RNA (Y RNA )
Gene: Miscellaneous RNA gene on chromosome 19 (6,572,956 to 6,573,057, reverse strand). Ensembl gene ENSG00000199223.
Homologues: Orthologues: chimpanzee Y_RNA (100% identical), guinea pig Y_RNA (93% identical). Paralogues in human: RNY3 (94% identical), Y_RNA (93% identical), Y_RNA (92% identical), RNY3P1 (91% identical), Y_RNA (91% identical), Y_RNA (90% identical), Y_RNA (89% identical), Y_RNA (88% identical), RNY3P16 (87% identical), RNY3P2 (87% identical), Y_RNA (87% identical), RNY3P13 (86% identical), and 97 more.